SALL4 (spalt like transcription factor 4)
Diseases named in the same sentence as SALL4 in open-access papers (continued):
Sharing a sentence is not in itself a finding about the gene and the disease.
cancer (continued). "Conversely, silencing of SALL4 can increase PTEN expression and reduce AKT activity in cancer cells." (PMID 41163374, 2025). "Our findings identify SALL4 as a CRL3REN substrate and a promising therapeutic target in SHH-dependent cancers." (PMID 38062245, 2024). "IHC stains demonstrated that the cancer cells were positive for anti-AFP, anti-CEA, anti-SALL4 (spalt like transcription factor 4)." (PMID 38167074, 2024). "SALL4 can regulate VEGF expression by targeting the SALL4/VEGF pathway, thereby inhibiting cancer angiogenesis." (PMID 39703839, 2024). "Considering the important role of SALL4 in GIT cancers, additional in-depth studies can be performed to explore the functions of the different SALL4 isoforms in cancers." (PMID 38584262, 2024). "AED is a carcinoma with tubulopapillary growth of columnar cells with clear cytoplasm expressing oncofetal proteins, including AFP, GPC3, and/or SALL4." (PMID 38851063, 2024). "SALL4 is a C2H2 zinc finger transcription factor that is essential for embryonic development and frequently activated in many cancers." (PMID 37674200, 2023). "However, the role of SALL4 in cancer angiogenesis remains unknown." (PMID 37525212, 2023). "A particular oncogenic network was unraveled where Netrin‐1 and TGF‐β1 collaborate to induce SALL4 expression in CAF and drive their cancer‐stemness‐promoting functions." (PMID 36587397, 2023). "Among HCCs with Wnt/β-catenin activation, some show an aggressive phenotype that is positive for EMT transcription factors and cancer stem cell markers, including CK19, EpCAM, and SALL4." (PMID 35053606, 2022). "Consistently with previous studies, our results indicate that SALL4 in concert with other stemness markers like OCT4, NANOG, and SOX2 can drive reprogramming of cancer cells toward a CSC-like phenotype mediated by the TWIST1 expression." (PMID 36474162, 2022). "It has been demonstrated that LINC-ROR regulates the pluripotency levels of TFs, including SALL4, LIN28, OCT4, SOX2, and NANOG via acting as a miRNA-145 sponge, leading to the preservation of hESCs and cancer stem cells undifferentiated status." (PMID 33745265, 2021). "The explicit role of SALL4 in COAD can be attributed to its pivotal role in cell proliferation, apoptosis, invasive migration, chemoresistance, and the maintenance of cancer stem cells." (PMID 34746134, 2021). "SALL4 is a well-recognized oncogene; however, SALL1–3 play dual roles depending on the cancer context and stage of the disease." (PMID 34944911, 2021). "LncRNAs play key roles in tumorigenesis and many aspects of cancer development; therefore, evaluating the probable correlation between LINC-ROR and SALL4 in GC development is needed." (PMID 33745265, 2021). "In recent years, there has been substantial progress in our knowledge of the molecular pathways by which stem cell factor SALL4 regulates the embryonic stem cell (ESC) properties, developmental events, and human cancers." (PMID 29308206, 2018). "The six selected genes (TWIST1, LAMB1, THY1, EZH2, SALL4, and TCF3) are involved in cell differentiation, HCC cancer stem cells (CSCs) markers, and CSCs involved pathways." (PMID 28158312, 2017). "Aberrant amplification of SALL4 and ZNF217 serve as unfavorable predictors of survival expectancy among cancer sufferers, revealing great potential as targeted spots in future therapeutics." (PMID 27007163, 2016). "Our study on SALL4 as a repressor and its association with the NuRD complex is only the first step in understanding the SALL4-mediated epigenetic modification in ESC, adult stem cells and cancer stem cells." (PMID 19440552, 2009).
cancer (continued). "This reduction correlated with increased expression of stem cell markers, such as PROM1, CK19, DLK1, SALL4, and EPCAM, suggesting that low SLC2A2 levels may promote cancer stem cell traits, malignancy, and therapeutic resistance." (PMID 40279337, 2025). "Several studies have established that elevated SALL4 expression correlates with poorer survival rates in cancer patients, though these do not specify individual protein isoforms." (PMID 39905414, 2025). "Spalt-like transcription factor 4 (SALL4), a cancer stem cell (CSC) marker, has been identified as a promising biomarker and diagnostic/therapeutic target owing to its overexpression in various cancers, including GIT cancers, with adverse progression and poor outcomes." (PMID 38584262, 2024). "Human Sal-like 4 (SALL4), a highly important player in the early and mid-stage of fetal liver development, becomes silenced in adults’ liver as one of the few embryonic stem cell (ESC) genes establishing contact with cancer cells." (PMID 36575044, 2022). "Since stemness markers determine self-renewing cell populations with CSC characteristics in various types of cancers, we next examined the effect of TWIST1 overexpression on the induction of stemness genes SALL4, OCT4, NANOG and SOX2 in KYSE-30 and YM-1 ESCC cells." (PMID 36474162, 2022). "The landmark discovery of a new class of molecular glues non-IMiD targeting SALL4 and other oncogenes has the potential to become a real disease modifying treatment and open a novel therapeutic perspective for several intractable cancer conditions." (PMID 36010677, 2022). "In our study several interesting genes were upregulated in GFP+ alone including MAGI2, SALL4, and WRAP53, most which had been implicated in human cancers and with no known role in alphaviral infection or disease." (PMID 36680176, 2022). "SALL4 expression is normally absent in most adult tissues, but is activated in various human cancers." (PMID 35482646, 2022). "Current reviews on SALL proteins’ role in cancer are available; however, they are only focused on SALL4 or SALL2, lacking an integrated view of the SALL family." (PMID 34944911, 2021). "A strong relationship between the CTA- and SALL4-specific T cell response and early-stage HCC was identified, suggesting a potential protective role of this T cell response in the partial control of cancer development." (PMID 34496797, 2021). "To comprehensively understand these three lncRNAs (BOLA3-AS1, AC124067.4, and AL161772.1) and four target RNAs (NINL, SALL4, TNFSF11, PHYHIPL), we performed differential expression, cancer stemness, immune subtype, TME infiltration, and drug sensitivity analyses." (PMID 34746134, 2021). "Let-7/miR-98-induced SALL4 depletion decreased the expression of MMP2/9, Fibronectin, n-cadherin, and increased E-cadherin, which correlated with reduced migration/invasion and EMT in an HCC in vivo cancer model." (PMID 34944911, 2021). "Moreover, SNHG12 was also reported to be involved in the tumorigenesis of other cancers by interacting with miR-129-5p/WWP1, miR-195/CCNE1, miR-125-5p/MDM4, miR-326/E2F1, and miR-15a-5p/SALL4 axes." (PMID 33294456, 2020). "In cancer cells with high levels of p‐TFCP2L1, CDK1, SALL4, and CD44 levels were significantly higher than in cells with low expression of p‐TFCP2L1, suggesting that a subset of p‐TFCP2L1‐positive cells could represent a population of bladder CSCs." (PMID 31709755, 2020). "SALL4 is expressed in human fetal liver, but not in healthy adult liver; however, SALL4 is re-expressed in a number of human cancers, particularly HCC." (PMID 29593314, 2018).
cancer (continued). "Although SALL4 was recently reported to over-express in various cancers and to regulate cell proliferation, apoptosis, migration/invasion, and stemness by targeting a variety of genes, there is no report about SALL4 regulation of host miRNA transcription." (PMID 29593314, 2018). "Our study is the first meta-analysis to conclude that SALL4 redundancy is a negative indicator towards long-term survival expectancy in solid malignancies, irrespective of cancer types or source regions." (PMID 27007163, 2016). "In general, the results suggested that the intensity and percentage of SALL4 immunostaining in cancer tissues were much stronger than those in adjacent non-cancerous tissues." (PMID 27329034, 2016). "Unlike blood malignancies and GSTs, few studies have focused on the molecular epidemiology of SALL4 in other cancers and there are no reports of SALL4 gene expression and its probable role in CRC to date." (PMID 23363002, 2013). "Surprisingly, IMiDs do not inhibit the growth of SALL4-expressing cancer cells." (PMID 40369156, 2025). "By integrating insights from transmembrane adaptor proteins, like TMEPAI, transcriptional regulators such as SALL4, oncoprotein coactivators similar to TCL1B, and cytokine signals akin to TGF‐β, we gain a more holistic understanding of how PI3K/AKT is hyperactivated in cancer." (PMID 41163374, 2025). "However, the prognostic relevance of the SALL4 expression in PDAC and the mechanisms governing SALL4 expression in such cancers have so far not been thoroughly investigated." (PMID 36587397, 2023). "It will also be of interest to test whether Sall4 overexpression can alter regenerative processes that are not examined in this study, as well as cancer cell phenotypes." (PMID 35482646, 2022). "It has been observed that the interaction between SALL4 and RBBp4 may recruit the NuRD complex to the PTEN promoter; as a consequence, PTEN repression and activation of PI3K/AKT pathway are produced, enhancing cancer cell proliferation." (PMID 36362083, 2022). "In addition, FOXC2, SALL4, CSF1 and BMI1 mRNA levels were also increased in Hep3B-TFF3 cells, all of which have recently been suggested to be involved in promoting CSC-like characteristics in various cancer cells." (PMID 28445151, 2017). "Furthermore, it is well-known that cancer cells undergoing EMT share the properties of stem cell-like cells, which could indicate SALL4 as a CSC marker in ESCC." (PMID 27329034, 2016). "Thus, the role of SALL4 in cancer is still controversial, while its function in HCC has not yet been determined." (PMID 24860834, 2014). "However, the association of SALL4 with the survival of GC patients is not well-understood, and the role of SALL4 in cancer progression is still unknown." (PMID 33644042, 2021). "Current reviews of SALLs have focused only on SALL2 or SALL4, lacking an integrated view of the SALL family members in cancer." (PMID 34944911, 2021). "Over-expression of SALL4 and ZNF217 were negatively correlated with clinical prognosis of 3-year, 5-year, 10-year and disease-free survival in solid malignancies, irrespective of cancer types, source regions, mean-age and sex predominance." (PMID 27007163, 2016). "However, deepC-SV could not find any SE involved with three cancer-related genes (17.6%, 3/17): NFATC2 and SALL4 in MCF7, TERT in HCC1954." (PMID 39322849, 2024). "However, both large and small carcinoma cells were totally c-Kit-negative, CD34-negative, αSMA-partially positive, PLAP-positive, SALL4-focally positive, AFP-negative, CD30-negative, glypican-3-slightly positive and Oct3/4-negative using immunohistochemical staining." (PMID 32990826, 2020).
adenocarcinoma (8 papers, 2016 to 2026). A common cancer characterized by the presence of malignant glandular cells. "The glandular component consisted of a well-to-moderately differentiated adenocarcinoma with clear-cell morphology and enteroblastic features, showing positivity for glypican-3 and SALL4 with focal alpha-fetoprotein expression." (PMID 41969299, 2026). "SALL4 expression was significantly upregulated in adenocarcinoma tissues compared to the matched normal lung tissues (P < 0.001)." (PMID 27705911, 2016). "SALL4 transcript level was analyzed in 226 adenocarcinomas and 20 adjacent normal lung tissue samples." (PMID 27705911, 2016). "In parallel, the immunohistochemical profile of these adenocarcinomas is characterized by the loss of INI-1 expression, positivity for CK7, CK20 (focal) and CDX2 (focal), as well as positivity for yolk sac markers like glypican-3, alpha fetoprotein and SALL4." (PMID 35326613, 2022). "The immunohistochemical profile of these adenocarcinomas is more complex, and, besides the loss of INI-1 expression, includes positivity for CK7, CK20 (focal) and CDX2 (focal), as well as for yolk sac markers including glypican-3, alpha fetoprotein and SALL4." (PMID 35326613, 2022). "- Gland-forming adenocarcinoma without clear cells. - Positive IHC for AFP and/or SALL4." (PMID 34977100, 2021).
infection (6 papers, 2010 to 2024). The state of being infected such as from the introduction of a foreign agent such as serum, vaccine, antigenic substance or organism. "Depletion of both Wapal and Sall4 induced a loss of compact, spherical colonies indicative of differentiation 6 days after infection." (PMID 27087855, 2016). "The qRT-PCR and Western blot analysis verified that SALL4 was overexpressed after infection with EX-SALL4 lentiviral particles (p < 0.01)." (PMID 30423818, 2018). "Following infection, morphological examination by light phase microscopy revealed distinct morphological changes in SALL4-reduced ES cells when compared with the control." (PMID 20505821, 2010). "Next, we generated reconstituted cell lines stably expressing AGIA-AirID-CRBN-WT (wild type) or -YW/AA by infection of CRBN−/− HEK293T cells with lentivirus, and we performed STA-PDA using the reconstituted HEK293T cells transiently transfected with Myc-SALL4 and Myc-IKZF1 expression vectors." (PMID 35013300, 2022).
hematological malignancies (3 papers, 2017 to 2019). "Unlike its absence or decreased level in most adult tissues, SALL4 is re-expressed in various human tumors, including hematologic malignancies, as well as liver, gastric, lung, endometrial, and breast cancers." (PMID 28800701, 2018).
blood cancer (2 papers, 2011 to 2021). "Three SALL4 functional isoforms were identified in blood cancers in humans and mice (A, B, and C)." (PMID 34944911, 2021). "We then sorted SP and non-SP cells from four different blood cancer cell lines, HL-60, RPMI8226, NB-4 and KG1a cells, and measured the expression of SALL4 in SP cells and non-SP cells of each cell line by qRT-PCR." (PMID 21526180, 2011).
digestive system cancer (2 papers, 2017 to 2024). A primary or metastatic malignant neoplasm involving any part of the digestive system. "In this review, we summarize current research data on the roles of SALL4 in gastrointestinal tract cancers and the underlying mechanisms." (PMID 38584262, 2024). "SALL4 was firstly studied in germline cells from solid tumors and it resulted a valid diagnostic marker with a good sensitivity, but only later it was associated with poor prognosis in digestive system cancers." (PMID 28160555, 2017). "SALL4 mediates EMT in CRC cells, as in other gastrointestinal tract cancers, with the Wnt/β-catenin pathway potentially involved in this process." (PMID 38584262, 2024).
genetic disorders (2 papers, 2018 to 2024). "Our findings that thalidomide and its derivatives induce degradation of SALL4, provide a direct link to genetic disorders of SALL4 deficiency, which phenocopy many of the teratogenic effects of thalidomide." (PMID 30067223, 2018).
benign tumors (1 paper, 2022). "IHC analysis of SOC tissues compared to benign tumors and normal tissue samples indicated that SALL4 protein expression is upregulated in SOCs in comparison to benign tumors and normal tissues." (PMID 35090523, 2022). "The expression level of SALL4 was evaluated in benign tumors and normal tissue samples." (PMID 35090523, 2022).
cardiovascular diseases (1 paper, 2019). "Here, eleven variants found in SALL4 and TBX5 were previously evaluated or associated with cardiac malformations or cardiovascular diseases 34,36–38." (PMID 31388035, 2019).
SALL4 also shares sentences with these, for which no sentence is quoted: B-cell lymphoblastic leukemia (4 papers); Townes-Brocks Syndrome 1 (4); Baraitser-Winter syndrome (3); bladder cancer (3); neuroblastoma (3); Papillorenal syndrome (3); anemia (2); developmental delay (2); dysplasia (2); epithelial neoplasm (2); germ cell cancer (2); germ cell ovarian tumors (2); invasive ductal carcinoma (2); rhabdomyosarcoma (2); testis tumours (2); Thrombocytopenia (2); vascular tumor (2); achondroplasia (1); adenocarcinoma in situ (1); adenomatoid odontogenic tumor (1); anaplastic large cell lymphoma (1); aplastic anemia (1); arthrogryposis (1); asphyxiating thoracic dystrophy 3 (1); auricular malformation (1); autism (1); autosomal dominant disease (1); bile duct tumor (1); biphasic mesothelioma (1); brain inflammation (1).
A further 51 diseases each share a sentence with SALL4 in 1 paper.